IL9 (interleukin 9)
Diseases named in the same sentence as IL9 in open-access papers (continued):
Sharing a sentence is not in itself a finding about the gene and the disease.
tumor (continued). "IL-9 impedes adaptive immunity responses and the maturation of T cells, while IL-10 can assist in tumor immune surveillance escape." (PMID 27169467, 2016). "In another study of mice bearing B16F10 melanoma, homozygous knockout of IL9RA resulted in increased tumor growth, and administration of IL9 to wildtype tumor-bearing mice reduced tumor growth." (PMID 27655702, 2016). "Although IL-9 possibly promotes lymphomagenesis, it can also inhibit the growth of melanoma either directly or by promoting anti-tumor immunity." (PMID 27148488, 2016). "Altogether, these findings suggest that IL9 signaling promotes activation of immune cells to recognize cancer cells and has tumor suppressive functions." (PMID 27655702, 2016). "Compared with healthy individuals, CRC patients showed decreased levels of IL-9 in the serum and intestinal tissues, and IL-9 expression in these samples negatively correlated with tumor progression." (PMID 27148488, 2016). "IL-9 produced by TH9 cells elicits anti-tumor immune responses through both direct and indirect regulatory mechanisms." (PMID 27589682, 2016). "In a pulmonary melanoma model, it was found that neutralization of IL9 resulted in increased tumor growth and reduced leukocyte infiltration in the tumors." (PMID 27655702, 2016). "Some articles described IL-9 ability to promote the survival of a large number of different cell types, including T cells, mast cells and eosinophils, neurons, tumor, and epithelial cells." (PMID 26078482, 2015). "Nevertheless, IL-9 can lead to either a favorable or unfavorable clinical prognosis depending on the tumor." (PMID 24722378, 2014). "They do so by producing various cytokines, including TGF-, IL-10, and IL-9, thereby promoting tumor growth." (PMID 25356878, 2014). "On the other hand, IL-17 indirectly attracts Foxp3+ Tregs, enhances their suppressor function, and induces IL-9 production by Foxp3+ Tregs; in turn, IL-9 strengthens the survival and protumor effects of mast cells in the tumor microenvironment." (PMID 22615941, 2012). "Taken together, these data suggested that cytokine IL-9 by Treg cells plays an important role in mast cell-mediated tumor promotion in tumor microenvironment." (PMID 20111717, 2010). "After intraperitoneal injection of tumor cells, recipient mice (control background = IL-9-negative or IL-9 transgenic mice) developed tumours within 4–10 weeks." (PMID 21297223, 2010). "Analysis by cytokine array showed a negligible signal for IL-10 and IL-9 in a pool of three splenic tumour tissue samples, which was equivalent to NSC splenic samples." (PMID 20161707, 2010). "The interference of IL-9 signaling by either IL-9 neutralizing antibody or depleting Treg cells weakened BMMCs-mediated MDSC infiltration toward tumor, and attenuated BMMCs-enhanced tumor growth." (PMID 20111717, 2010). "Moreover, in vitro studies indicated that IL-9 increased the cytotoxicity of tumour-specific CD8+ T cells in mice." (PMID 39325360, 2025). "However, Th9 cells, a major subset of CD4+T cells, have been shown to produce high levels of IL-9 and exert anti-tumor effects in certain solid tumors such as breast cancer and lung cancer." (PMID 39958351, 2025). "These dual roles underscore the importance of tumor-intrinsic IL-9R expression and the tumor microenvironment in determining whether IL-9 promotes or inhibits tumor growth." (PMID 41030439, 2025). "Inflammatory cytokines, including IL-1α, IL-3, IL-9, and IL-12, are pivotal in amplifying the immune response, particularly in immune surveillance and the clearance of tumor cells, by facilitating the proliferation, differentiation, and activation of immune cells." (PMID 40426998, 2025). "Meanwhile, IL-9 also contributes to tumor development through indirect mechanisms." (PMID 41346580, 2025). "These Th9 cells produce IL-9, contributing to robust anti-tumor immunity." (PMID 41163402, 2025).
tumor (continued). "Lu’s experiments showed that targeting and blocking IL-9 could effectively inhibit tumor growth in a PC mouse model." (PMID 39958351, 2025). "Additionally, IL-9 enhances anti-tumor immunity by activating mast cells and indirectly boosting the cytotoxic functions of CD8+ T cells and natural killer (NK) cells." (PMID 39852828, 2025). "The results demonstrate that mice treated with the combination of Xcl1-E6E7 and IL-9 experienced earlier tumor regression and ultimately achieved a complete remission rate of 3 out of 5, compared to a 0 out of 5 remission rate for those treated with Xcl1-E6E7 alone." (PMID 39852828, 2025). "Whether increased numbers of CTL next to tumor cells in IL-9-high p16− HNSCC also indicate an increased anti-tumor immune response and thus might serve as a biomarker deserves further investigation." (PMID 40497965, 2025). "Furthermore, high levels of CXCL10, IL-9, and CCL4 were associated with significantly higher numbers of T cells, especially for CTL with direct contact to tumor cells, whereas for VEGF the opposite effect was observed in the tumor stroma." (PMID 40497965, 2025). "In contrast, IFN-γ, IL-16, IL-1ra, IL-8, and IL-9 were related to tumor cell type." (PMID 41048959, 2025). "We then evaluated the anti-tumor efficacy of combining Xcl1-E6E7 with the IL-9 plasmid." (PMID 39852828, 2025). "Furthermore, the proliferation of tumor cells was suppressed, and a greater number of apoptotic tumor cells were detected after Nivolumab treatment exclusively in the group of patients with high levels of IL-9+ T cells." (PMID 39325360, 2025). "Furthermore, IL-33 contributes to the induction of Th9 cells, a subset of Th cells that produce IL-9 and have potent anti-tumor effects." (PMID 41163402, 2025). "More IL-9 receptor-expressing tumor-infiltrating leukocytes were observed after the vvDD-IL-9 treatment compared to the vvDD treatment, indicating that the IL-9/IL-9 receptor signal pathways are involved in the antitumor effects elicited by vvDD-IL-9 treatment." (PMID 38473379, 2024). "The anti-tumor efficacy of IL-9 neutralization has been also recently explored." (PMID 39281678, 2024). "In a mouse model of colorectal cancer, IL-9 suppressed tumor growth through CD8+ T cell activation." (PMID 39281678, 2024). "Thus, the fact that tumor cells themselves can secrete IL-9 in response to drugs, such as OSU13, is intriguing and warrants further investigation beyond this study." (PMID 38900577, 2024). "The importance of IL-9 in tumour progression is controversial." (PMID 38920685, 2024). "Notably, M1 macrophages induced by IL-9 recruit anti-tumor immune cells into the tumor tissue through the chemoattractant macrophage chemokines CCL3/4 and CXCL9/10, thereby triggering anti-tumor immunity." (PMID 38892411, 2024). "In the context of the associations with IL-4, IL-9, and TNF-α, high SIGLEC9 expression may have a suppressive effect on the immune system, helping the tumor evade elimination by immune cells." (PMID 39727942, 2024). "Moreover, neutralizing anti-IL-9 or anti-IL-9R antibodies significantly inhibit tumor growth in mouse models of lymphoma." (PMID 39281678, 2024). "In addition, we found that a lack of de novo fatty acid biosynthesis augmented the antitumor immunity of Th9 cells via an increase in IL-9 production in mouse tumor models." (PMID 39187636, 2024). "These drugs, in combination with therapies aimed at neutralizing the T cell suppressive activities of IL-6, IL-9 and/or IL-10, may reasonably help reducing immune evasion of tumor cells, thereby ameliorating the clinical management of the disease." (PMID 39281678, 2024). "However, the precise and consistent role of IL-9 in tumor immunity remains enigmatic and subject to controversy." (PMID 38840908, 2024). "IMs might also play a role in LC, as the presence of IMs and their IL-9-stimulated arginase production correlated with tumor growth in mouse lungs." (PMID 36809334, 2023).
tumor (continued). "IL-9 can also potently promote an anti-tumor immune response in different murine models." (PMID 37189417, 2023). "IL-9 is reportedly important in the anti-tumor immune response." (PMID 37228617, 2023). "However, IL-9R knockdown in CMT167 cells abrogated the IL-9-driven tumor growth inhibition and enhanced T-cell infiltration." (PMID 37189417, 2023). "Moreover, upon antigenic activation in vitro, PB CAR-T cells released lower levels of IFN-γ, IL-6, IL-10, TNF-α, CCL2, CXCL10, and GM-CSF than Lenti CAR-T cells, but demonstrated a robust release of IL-9, indicative of a distinct anti-tumor response pathway." (PMID 37228617, 2023). "The potential role of TH9 cells in anti-PD-1-induced anti-tumor immune response may extend to other cytokines beyond IL-9." (PMID 37189417, 2023). "The in vivo data revealed that intratumoral IL9-polarized TAMs could play a central role in recruiting antitumor immune cells and facilitating their infiltration into the tumor." (PMID 36968220, 2023). "Our previous study found that the number of tumor nodules in the lungs of the mice intravenously injected with IL9-expressing B16F10 was significantly less than that of the control groups, and pulmonary M1 macrophages were the population most significantly increased in the lungs of those mice." (PMID 36968220, 2023). "Similarly, IL-9 mRNA levels were higher in tumor cells derived from nasal natural killer/T-cell lymphoma compared to healthy controls." (PMID 36980536, 2023). "A potential explanation may be that IL-9 is also a prototypical mast cell growth factor and may exert tumour-promoting properties through mast cells." (PMID 37455828, 2023). "Therefore, although considered as part of type 2 immunity, studies are consistent with IL-9 inducing anti-tumour immunity through cross-activating type 1 immune INFγ producing cells such as CD8+ T cells and Th1 cells." (PMID 37455828, 2023). "IL-2, IL-15, and IL-21 in the IL-2 cytokine family play a positive role in anti-tumor effects, and IL-4, IL-7 and IL-9 possess pleiotropic functions, with diverse roles in cancer immunity as they can have pro-tumorigenic functions as well as anti-tumorigenic characteristics." (PMID 36936961, 2023). "Therefore, the role of IL-9 in tumorigenesis is likely dependent on the specific immune cell landscape of the tumour microenvironment depending on the cancer type." (PMID 37455828, 2023). "Several mechanisms of the anti-tumor function of IL-9 could contribute to the observed synergy with anti-PD-1 treatment." (PMID 37189417, 2023). "CCT3-mediated Th2 deviation in tumor microenvironment may link to a worse outcome for LUAD, since Th2 cytokines IL-4 IL-5, IL-9 and IL-13 trigger the differentiation of tumor-associated M2 macrophages." (PMID 36918801, 2023). "Besides the direct inhibitory effect of IL-9 on tumor cells, it was shown that IL-9 and IL-9-producing T-cells provide a unique inflammatory environment in tumor tissues, which promotes tumor-specific T-cell responses, particularly CTLs." (PMID 37835465, 2023). "Additionally, IL-9 increased PD-L1 expression in tumor cells and PD-1 expression in T cells which explained the synergistic effects observed upon PD-1 blockade." (PMID 37189417, 2023). "Specifically, IL-9 can promote cancer cell proliferation and protect tumor cells from apoptosis." (PMID 36936961, 2023). "Importantly, the IL-9 signaling pathway has been found to be particularly effective in enhancing the anti-tumor response of CAR-T cells." (PMID 37228617, 2023). "These range from anti-PD-1/PDL-1 therapy for NSCLC patients with abundant M2 infiltrate, promotion of C9 secretion in AMs to suspend NSCLC progression, IL-9 signaling blockade, as well as skewing the M2 phenotype toward the M1 phenotype to elevate tumor-fighting properties within the TME." (PMID 36809334, 2023). "Next, we further elucidated how immune cells could be recruited by colocalizing IL9 and macrophages in the tumor mass." (PMID 36968220, 2023).
tumor (continued). "During the last decade, multiple studies have revealed the contribution of IL-9 to tumor immunity." (PMID 37189417, 2023). "But recently, evidence increasingly suggests that IL-9 also exerts anti-tumor effects." (PMID 36936961, 2023). "Some of the mechanisms that have been proposed through which IL-9 could promote tumor growth include promoting the survival of lymphoma cells by reducing their oxidative stress and inducing immunosuppression from Treg cells." (PMID 36980536, 2023). "Further studies suggested that IL-9 derived from tumor infiltrating T cells (TILs) as well as the tumor cells themselves might influence the T regulatory cells infiltrating the tumor." (PMID 35514957, 2022). "For instance, TGFβ could be identified as a potent inhibitor of IL-6-mediated tumor-supportive effects, whereas Th9 cell-released IL-9 is apparently able to increase I-L6 and IL-9 production by intratumoral Th9 cells in an auto-amplifying loop." (PMID 36428508, 2022). "In CRC, ILC2s suppress tumor by producing IL-9, but maintain pro-tumor effect by expressing PPARγ." (PMID 35720302, 2022). "In the majority of solid tumors, IL-9 could directly promote the apoptosis of tumor cells or activate the innate and adaptive anti-tumor immunity." (PMID 35211408, 2022). "These seemingly conflicting effects of IL-9 on tumor growth among tumor models in different organs could be due to the diverse pool of IL-9-responding cells in the specific tumor microenvironment." (PMID 35778404, 2022). "Both IL-9 and IL-27 are pleiotropic cytokines that could induce innate/adaptive immune responses and promote tumor cell apoptosis by enhancing the action of cytotoxic T lymphocytes." (PMID 36615662, 2022). "IL-9 mediates anti-tumor effects through multiple mechanisms including impacting the function of T cells, mast cells and dendritic cells (DCs), and by directly killing tumor cells." (PMID 35778404, 2022). "Thus, IL-9 controls tumour cell proliferation in colorectal neoplasias via IL-6 and impairs barrier function markedly." (PMID 35793807, 2022). "To understand how IL-9 signaling affects the transcriptional landscape of lung macrophages, we compared the gene expression of WT and Il9r−/− macrophages from intact lungs of tumor-bearing mice." (PMID 35778404, 2022). "IL-9 and Th9 was found to have both anti-tumor and pro-tumor effect." (PMID 35795670, 2022). "Finally, anti-IL-9 antibody immunotherapy resulted in suppression of tumor development even in established experimental NSCLC and was associated with reduced IL-10 production in the lung." (PMID 35514957, 2022). "Mechanistically, the IL-9/macrophage axis requires arginase 1 (Arg1) to mediate tumor growth." (PMID 35778404, 2022). "Continuously, lamina propria cells showed more IL-9-expressing CD3+ T cells in the tumour tissue." (PMID 35793807, 2022). "In tumor immunity, IL-9 has garnered interest as a potent effector in adoptive cell therapies." (PMID 35778404, 2022). "Similarly, tumor interleukin-9 (IL-9) levels were higher in BCW0 mice compared to both BCW12 and BCW12OFS mice (p < 0.001)." (PMID 35681702, 2022). "Isolated LPMCs from AOM/DSS tumours were examined in terms of the expression of IL-9." (PMID 35793807, 2022). "IL-9 could directly influence the survival of tumor cells, or activate mastocytes and recruit DCs to the tumor site, and it indirectly participates in tumor immunity." (PMID 35211408, 2022). "Together, these results suggest that CD4-derived IL-9 promotes tumor growth and IM expansion." (PMID 35778404, 2022). "Importantly, tumor growth is mediated when interstitial macrophages are the only IL-9-responsive cell in the system, supporting a central role of these cells in the tumor microenvironment." (PMID 35778404, 2022). "IL-9 is responsible of the survival of mast cells in the tumor microenvironment." (PMID 36430483, 2022). "IL-9 plays multi-faceted roles in inflammation, infection, and tumor immunity." (PMID 35795670, 2022).
tumor (continued). "Cytokine secretion, such as interleukin-4 (IL-4), IL-5, IL-9, IL-13, and amphiregulin (Areg), by type 2 innate lymphoid cells (ILC2s) is indispensable for homeostasis, remodeling/repairing tissue structure, inflammation, and tumor immunity." (PMID 35592688, 2022). "The contribution of IL-9 or IL-9-producing cells in tumor immunity is model-dependent." (PMID 35778404, 2022). "Moreover, in addition to tumor infiltrating lymphocytes, also lung tumoral cells have the capacity to produce IL-9." (PMID 35514957, 2022). "Il-6 and Il-9 expression positively correlated in AOM/DSS tumour tissue." (PMID 35793807, 2022). "Tumour numbers, tumour size, and tumour score in IL-9 knockout mice were significantly reduced." (PMID 35793807, 2022). "IL-9 plays an anti-tumor role in solid tumors, such as melanoma and breast cancer." (PMID 35211408, 2022). "However, the anti-tumor effect of transferred Th9 cells is indeed dependent on IL-9, as neutralization of IL-9 in the treated mice abolishes the antitumor function of the injected Th9 cells." (PMID 36241625, 2022). "Since IL-9 was induced in the tumoral region of the lung, we asked whether the tumor cells themselves would produce IL-9." (PMID 35514957, 2022). "Finally, we directly analyzed the pro-tumoral function of IL-9 on the tumor cell line L1C2 by using cell counts, Ki67 and AnnexinV/PI as proliferation and apoptosis markers, respectively." (PMID 35514957, 2022). "This crucial “anatomical” difference might account for the opposing functions of IL-9 in neoplasias, and suggests potentially different outcomes of anti-cancer therapies based on anti-IL-9 antibodies." (PMID 34944921, 2021). "In human basophils, IL-33, in synergy with IL-3, stimulates IL-9 production, which may strengthen tumor immunity." (PMID 34209038, 2021). "Th2 cytokines such as IL-4, IL-10, IL-5, IL-9, and IL-6 can down-regulate tumor-specific immunity." (PMID 34222249, 2021). "In addition to IL-9, in vitro differentiated Th9 cells also produce IL-101 while Th9 cells eliminate tumor in vivo by triggering IFN-γ production by CD8+ T cells." (PMID 34075041, 2021). "FMT from conventional mice into GF mice restores IL-9 production and decreases tumor growth." (PMID 33708214, 2021). "Interestingly, recent research has suggested that IL-9 can have both a protumorigenic and antitumorigenic role in the pathogenesis of neoplasia." (PMID 33803218, 2021). "However, Th9 cells and their anti-tumor cytokine IL-9 are powerful anti-tumor agents, which can be exploited in cell therapy." (PMID 33498483, 2021). "In addition, IL-33 can facilitate the differentiation of IL-9 producing Th cells (Th9), conferring their anti-tumor response in melanoma." (PMID 34209038, 2021). "Moreover, the high levels of Th9-secreted IL-9 found in Cutaneous T-Cell Lymphoma also participate in tumor development by reducing the oxidative stress of leukemic cells." (PMID 34944921, 2021). "Wan and colleagues recently defined IL-9 as a “double-edged sword” in tumor immunity." (PMID 34944921, 2021). "Moreover, they showed that neutralizing anti-IL-9 or anti-IL-9R antibodies significantly inhibit tumor growth in mouse models of lymphoma." (PMID 34944921, 2021). "Interleukin 9 (IL-9), a soluble factor secreted by immune cells, has been found in several tumor niches where, depending on the specific tumor type, it either promotes or counteracts tumor development." (PMID 34944921, 2021). "In addition, two studies suggested the importance of IL-9 specifically to immune-mediated limitation of tumor growth." (PMID 34675938, 2021). "HIF1α promotes Th9 cell differentiation: (i) metabolically through TCA cycle metabolite, Succinate, and (ii) transcriptionally by transactivating Il9 and Nos2 gene loci, further enhancing Th9 cell polarization and Th9 cell-mediated anti-tumor effector functions." (PMID 34075041, 2021). "IL-9 is also an important tumor immune-related cytokine, mainly produced by Th9 cells." (PMID 34386015, 2021).